HMGA1 (high mobility group AT-hook 1)
Diseases named in the same sentence as HMGA1 in open-access papers (continued):
Sharing a sentence is not in itself a finding about the gene and the disease.
thyroid cancer (11 papers, 2014 to 2024). "Recently, reduced miR-603 has been implicated in malignant transformation of thyroid cancer cells in response to high mobility group A1 (HMGA1) expression." (PMID 28036267, 2017). "Moreover, the expressions of S100A13 and HMGA1 in thyroid carcinoma were shown to be associated with the patient sex and tumor types, which is not be reported in other cancers previously." (PMID 27008379, 2016). "Based on experiments using rat and human thyroid cancer cells, high HMGA1 expression can stimulate the activation of caspase-3 and initiate cell apoptosis." (PMID 35629376, 2022). "Its promoter is methylated after binding with HMGA1, increasing the number of anaplastic cancer cell lines and promoting the progression of thyroid cancer." (PMID 35864955, 2022). "HMGA1 pseudogenes are difficult to detect in well differentiated thyroid cancer, and are only highly expressed in anaplastic thyroid carcinomas, and upregulate the level of HMGA1 protein to exert carcinogenic activity." (PMID 35864955, 2022). "Downregulation of HMGA1 expression inhibited the proliferation, migration, and invasion of thyroid cancer cells." (PMID 36479041, 2022). "The further clarification of underlying molecular events would be helpful for understanding the role of S100A13 and HMGA1 in the progression of thyroid cancer." (PMID 27008379, 2016). "The effect of siRNA-mediated HMGA1 knockdown on thyroid cancer cellular proliferation and invasion were evaluated by MTT, colony formation assays and transwell assays." (PMID 27008379, 2016). "The results suggest that HMGA1 was involved in the effect of S100A13 on thyroid cancer growth and invasion by modulating the expression of Snail and E-cadherin." (PMID 27008379, 2016). "This study establish the first link between S100A13 and HMGA1 in thyroid cancer, providing further evidence of the pivotal role of HMGA1 in thyroid cancer progression." (PMID 27008379, 2016). "In summary, this is the first report for the association between HMGA1 and S100A13 expression in the modulation of thyroid cancer growth and invasion." (PMID 27008379, 2016). "In this study, we determined the effects of S100A13 on HMGA1 expression in thyroid cancer cells and examined the role of HMGA1 in thyroid cancer progression." (PMID 27008379, 2016). "This is the first report for the association between HMGA1 and S100A13 expression in the modulation of thyroid cancer growth and invasion." (PMID 27008379, 2016). "HMGA1 expression in thyroid carcinoma also showed a statistically significant correlation with the patient sex and tumor types (P = 0.016 and 0.003)." (PMID 27008379, 2016). "TGF-β1 can enhance the activity of the HMGA1 promoter and induce the expression of HMGA1 through extracellular signal-related kinase and phosphoinositide 3-kinase, so HMGA1 may exist as a tumour-specific marker for thyroid cancer." (PMID 35864955, 2022). "In addition, a tissue microarray revealed that higher expressions of both S100A13 and HMGA1 were observed in thyroid cancer cases compared with that in normal thyroid cases." (PMID 27008379, 2016). "Those tissue microarray data confirmed that S100A13 and HMGA1 expression were positively correlated in thyroid carcinoma, and it may be involved in the progression of thyroid cancer." (PMID 27008379, 2016). "In this study, we examined the effects of S100A13 and HMGA1 on thyroid cancer progression." (PMID 27008379, 2016). "To verify whether the two HMGA1Ps function as decoys in the regulation of HMGA1 protein levels also in human cancer, we analyzed the expression of HMGA1 and of the HMGA1Ps in a panel of differentiated and undifferentiated thyroid carcinomas by Western Blotting and Real-time PCR." (PMID 25268743, 2014). "Furthermore, S100A13 and HMGA1 expressions were found to be positively correlated (r = 0.316, P = 0.004), when analyzed regardless of thyroid cancer types." (PMID 27008379, 2016).
thyroid cancer (continued). "The expression of HMGA1 is absent or present only at low level in normal cell and adult tissues but are elevated in embryonic cells and many malignant neoplasias, including breast, pancreas, lung, ovary, colon and thyroid carcinomas." (PMID 27008379, 2016). "Furthermore, it was revealed that the siRNA induced HMGA1 could lead to the downregulation of Snail and upregulation of E-cadherin in both mRNA or protein levels in SW579 cells, resulting in the decrease of invasive abilities of thyroid cancer SW579 cells (P < 0.01)." (PMID 27008379, 2016).
esophageal squamous cell carcinoma (9 papers, 2016 to 2024). Esophageal squamous cell carcinoma (ESCC) is a type of esophageal carcinoma (EC) that can affect any part of the esophagus, but is usually located in the upper or middle third. "In this study, we report the poly ADP‐ribosylation (PARylation) of HMGA1 during DNA damage, leading to desensitization of esophageal squamous cell carcinoma (ESCC) cells to the poly(ADP‐ribose) polymerase 1 (PARP1) inhibitor, olaparib." (PMID 39690136, 2024). "Consequently, depletion of HMGA1 promotes ferroptosis and restores the sensitivity of esophageal squamous cell carcinoma (ESCC) to chemotherapy both in vitro and in vivo." (PMID 39595619, 2024).
melanoma (8 papers, 2013 to 2025). A malignant, usually aggressive tumor composed of atypical, neoplastic melanocytes. "Contact-dependent inhibition of melanoma cells by MCs has also been demonstrated in studies on HMGA1 biogenesis." (PMID 41373472, 2025). "High HMGA1 expression in metastatic tissue is related with reduced OS, whereas the reduced expression of HMGA1 limited the metastatic behavior of melanoma cells." (PMID 39126091, 2024).
metastatic tumors (8 papers, 2012 to 2023). "Cancer cells of metastatic tumors exhibited significantly higher expression level of HMGA1 than cancer cells of primary tumors from matched late-stage KPC mice." (PMID 37190324, 2023). "Cancer cells in metastatic tumors exhibited a significantly higher expression level of HMGA1 than those in primary tumors of human patients." (PMID 37190324, 2023). "The expression level of HMGA1 is low or undetectable in normal tissues, while high levels of HMGA1 can be observed in primary or metastatic tumors from diverse tissues, indicating a putative role for HMGA1 in neoplastic transformation." (PMID 35785026, 2022). "Taken together, these data suggest that HMGA1 plays a key role in breast malignancy and the progression of metastatic disease by modulating a specific gene network." (PMID 23945276, 2013). "This work, together with prior studies in diverse tumors, provide compelling evidence that HMGA1 is a master regulator in the evolution of primary tumors to metastatic disease." (PMID 23658826, 2013). "Our findings further implicate HMGA1 as a master regulator in tumor progression and suggest that targeting HMGA1 pathways could be effective in poorly differentiated, metastatic tumors." (PMID 23658826, 2013).
Sepsis (8 papers, 2007 to 2025). Sepsis is defined as life-threatening organ dysfunction caused by a dysregulated host response to infection. "Currently, there have been no reported studies on the related mechanisms of lncRNA IGF2-AS mediating HMGA1 in regulating nucleotide metabolism in sepsis, which is also the innovation of this study." (PMID 35082972, 2022). "qRT-PCR and WB detection showed that HMGA1 was highly expressed in EPCs of sepsis patients compared with the Healthy group." (PMID 35082972, 2022). "As a dynamic regulator of gene transcription and chromatin remodeling, HMGA1 played an important role in the pathological process of sepsis-induced cardiomyopathy." (PMID 35720285, 2022). "Subsequently, dNTP treatment with different concentrations was performed to investigate lncRNA IGF2-AS and HMGA1 effects on pyroptosis of EPCs in sepsis patients." (PMID 35082972, 2022). "We aimed to investigate lncRNA IGF2-AS and HMGA1 effects on pyroptosis of endothelial progenitor cells (EPCs) in sepsis patients and the mechanisms involved." (PMID 35082972, 2022). "lncRNA IGF2-AS regulated nucleotide metabolism by mediating HMGA1 to promote pyroptosis of EPCs in sepsis patients." (PMID 35082972, 2022). "We took EPCs of sepsis patients as the research object and explored lncRNA IGF2-AS and HMGA1 effects on the pyroptosis of EPCs in patients with sepsis, and the mechanisms involved in it through in vitro cell experiments." (PMID 35082972, 2022). "Our results suggested that lncRNA IGF2-AS regulated nucleotide metabolism by mediating HMGA1 to promote pyroptosis of EPCs in sepsis patients." (PMID 35082972, 2022). "In conclusion, in this study, we found that lncRNA IGF2-AS mediated HMGA1 to regulate nucleotide metabolism and promote pyroptosis of EPCs in sepsis patients." (PMID 35082972, 2022). "In human studies, as reported, lncRNA IGF2-AS binds HMGA1 to regulate nucleotide metabolism, promoting pyroptosis of endothelial progenitor cells (EPCs) in sepsis patients." (PMID 35720285, 2022). "We previously revealed that HMGA1 increased cardiomyocyte inflammation in a sepsis-induced cardiomyopathy model; HMGA1 promotes cardiac dysfunction in diabetic cardiomyopathy." (PMID 34513822, 2021). "As mesenchymal stromal cells (MSCs) are another mesenchymal cell with a significant influence on the inflammatory response during sepsis, we expanded our appraisal of HMGA1 from vascular smooth muscle cells to MSCs." (PMID 33438259, 2021). "In sepsis-induced cardiomyopathy models induced by LPS, the overexpression of HMGA1 exacerbates the inflammation and apoptosis of cardiomyocytes, while the silencing of HMGA1 alleviates the inflammation, but aggregates the apoptosis of cardiomyocytes." (PMID 35720285, 2022). "It was found that compared with the Healthy group, HMGA1 was highly expressed in the Sepsis group." (PMID 35082972, 2022). "Overexpression of HMGA1 aggravates cardiomyocytes inflammation in sepsis-induced cardiomyopathy." (PMID 35720285, 2022). "This indicates that lncRNA IGF2-AS plays a regulatory role in sepsis by combining with HMGA1." (PMID 35082972, 2022). "Moreover, we previously demonstrated that HMGA1 aggravated myocardial inflammation and apoptosis in a sepsis-induced cardiac injury mouse model by regulating both COX-2 and STAT3 signaling." (PMID 34513822, 2021). "We previously provided data indicating that HMGA1 could play an important role in sepsis-induced cardiomyopathy and diabetic cardiomyopathy." (PMID 34513822, 2021). "We hypothesized that HMGA1 is important in the function of mesenchymal stromal cells (MSCs), which are known to modulate inflammatory responses due to sepsis." (PMID 33438259, 2021). "In addition, recent reports demonstrated that HMGA1 functions as a mediator of the development of sepsis, as evidenced by its increased serum levels in patients with septic shock." (PMID 18045489, 2007). "Moreover, HMGA1 plays an important role in the pathogenesis and treatment of sepsis." (PMID 35720285, 2022).
Sepsis (continued). "It has been reported that blocking HMGA1-mediated pathways may improve the sepsis prognosis." (PMID 35082972, 2022). "In this paper, our study suggested that nucleotide metabolism in sepsis may be regulated by HMGA1." (PMID 35082972, 2022). "Therefore, we wanted to further investigate the roles of lncRNA IGF2-AS and HMGA1 in sepsis." (PMID 35082972, 2022). "In the studies about HMGs and programmed cell death in sepsis, HMGB1 and HMGA1 induce cell’s apoptosis and pyroptosis, and HMGB1 also induces necroptosis." (PMID 35720285, 2022). "In this study, we took EPCs of sepsis patients as the research object and explored lncRNA IGF2-AS and HMGA1 effects on pyroptosis of EPCs in sepsis patients and the involved mechanism through in vitro cell experiment." (PMID 35082972, 2022). "In short, HMGs, especially HMGA1 and HMGB1, are widely studied and demonstrated to be involved in the occurrence and development of sepsis." (PMID 35720285, 2022). "In the investigation of sepsis pathogenesis, the study has demonstrated that the lncRNA IGF2-AS plays a pivotal role in regulating deoxyribonucleoside triphosphate (dNTP) metabolism, mediated by Homo sapiens high mobility group AT-hook 1 (HMGA1)." (PMID 40454168, 2025). "Compared with Healthy group, lncRNA IGF2-AS, HMGA1, and TYMS were highly expressed in Sepsis group." (PMID 35082972, 2022). "MSCs expressing a dominant-negative HMGA1 cells showed improved function during sepsis." (PMID 35082972, 2022). "However, studies on lncRNA IGF2-AS and HMGA1 in sepsis have not been reported." (PMID 35082972, 2022).
adenoma (7 papers, 2015 to 2022). A neoplasm arising from the epithelium. "For example, early research demonstrated that HMGA1 expression could be useful in differentiating between thyroid follicular carcinoma and adenoma." (PMID 35805937, 2022). "To gain insight into the association of several Let-7 targets with tumorigenesis in vivo, we examined Hmga1, Hmga2, Arid3a, and Hif3a protein expression by immunostaining adenomas and adenocarcinomas, as well as adjacent normal tissue, from Lin28bLo/Let7IEC-KO mice." (PMID 26244988, 2015). "It has been reported that HMGA1 and HMGA2 nuclear expression levels are significantly higher in invasive adenomas than in non-invasive adenomas." (PMID 33574795, 2020). "The expression of both HMGA1 and HMGA2 was significantly increased in aggressive adenomas or macroadenomas compared to in non-aggressive ones." (PMID 31487906, 2019).
breast tumors (7 papers, 2013 to 2022). "Moreover, we identified a specific HMGA1 gene expression signature that was activated in a large subset of human primary breast tumours and was associated with poor prognosis." (PMID 23945276, 2013). "Our results provide further evidence on molecular signals governing breast tumor angiogenesis under the coordinate control of the two master regulators of tumorigenesis HMGA1 and FOXM1." (PMID 31311575, 2019). "We discovered that breast tumors with HER2 expression showed a higher expression level of HMGA1 and a higher expression level of HMGA1 was found in the ductal breast cancer cases compared with the lobular breast cancer cases." (PMID 25572132, 2015). "HMGA1 has also been reported to promote the progression of breast tumors by inducing EMT." (PMID 25572132, 2015). "Our results demonstrate that HMGA1 cooperates with FOXM1 in regulating the expression of a common gene network, enhancing the aggressiveness of TNBC cells, highlighting a dependence of breast tumor cells on HMGA1 and FOXM1 synergic action." (PMID 31311575, 2019). "Of note, there were also no small deletions of the HMGA1 and HMGA2 loci indicating rearrangements of these genes or chromosomal bands 6p21 or 12q14-15, respectively, as described in other biphasic breast tumors." (PMID 33292379, 2020).
cardiac hypertrophy (7 papers, 2013 to 2022). "In mice, haploinsufficiency of the Hmga1 gene causes cardiac hypertrophy and myelo-lymphoproliferative disorders; besides, Hmga1 is required for normal sperm development and a role for both Hmga1 and Hmga2 genes has been demonstrated in adipogenesis." (PMID 23936116, 2013).
esophageal cancer (7 papers, 2017 to 2024). A primary or metastatic malignant neoplasm involving the esophagus. "Consistently, we showed that overexpression of HMGA1 in esophageal cancer correlated with patients’ resistance to chemotherapy." (PMID 38383528, 2024). "In both subcutaneous tumour models and genetically engineered mouse models of in situ esophageal cancer, HMGA1 interference increased tumour sensitivity to olaparib." (PMID 39690136, 2024). "Esophageal cancer tissues in HMGA1 conditional knock-in (HMGA1KI/KIK14-cre+) mice displayed a much higher proportion of TKT-positive cells as compared with those in esophageal cancers induced in control mice (HMGA1KI/KI)." (PMID 39080260, 2024). "In contrast, HMGA1 was strongly expressed in the nucleus and weakly stained in the cytoplasm of esophageal cancer cells." (PMID 39080260, 2024). "Inhibition of HMGA1 was effective in sensitizing esophageal cancer cells to ferroptosis both in vitro and in vivo, providing a proof of concept for targeting HMGA1 in esophageal cancer treatment." (PMID 38383528, 2024). "Similar findings were obtained in esophageal tissues of mice treated with 4NQO for the induction of esophageal cancers demonstrating that HMGA1 was highly expressed in esophageal malignancies and rarely detected in adjacent normal esophageal tissues." (PMID 39080260, 2024). "Depletion of HMGA1 increases the cytotoxicity of DDP on esophageal cancer cells, in which ferroptosis plays a crucial role." (PMID 38383528, 2024). "It showed that HMGA1 was principally expressed in malignant epithelial cells of the esophageal carcinoma tissues." (PMID 39080260, 2024). "Indeed, in rapidly proliferating esophageal cancer cells, HMGA1 is one of the pivotal factors in protecting cells from chemotherapy damage, but the loss of HMGA1 is not the initial step in inducing programmed cell death." (PMID 38383528, 2024). "Future drug-discovery studies are warranted to identify HMGA1-specific inhibitors, which may expand the therapeutic arsenal for esophageal cancer and other cancers." (PMID 38383528, 2024). "To determine whether HMGA1 expression also plays a role in ESCC tumor growth, we constructed an HMGA1-knockdown cell line in mouse esophageal cancer AKR cells and inoculated these cells (2.5 × 106) subcutaneously into C57BL/6 mice." (PMID 39080260, 2024). "In conjunction with the findings that HMGA1 suppresses programmed cell death, we speculate that esophageal cancers with elevated expression of HMGA1 will be resistant to chemotherapy." (PMID 38383528, 2024). "Interestingly, the silencing of HMGA1 in the syngeneic tumors exhibited a greater inhibition of esophageal cancer growth compared to HMGA1 silencing in cells cultured, implying that HMGA1 acts as a more potent oncogene (tumor promoter) in the tumor microenvironment in vivo." (PMID 38725843, 2024). "Cell colony formation assay showed that knockdown of HMGA1 inhibited the proliferation of KYSE30 cells, an esophageal cancer cell line." (PMID 39080260, 2024). "To further validate the regulatory role of HMGA1 in the expression of TKT, we detected TKT in esophageal cancer in HMGA1 conditional knock-in (HMGA1KI/KIK14-cre+) mice." (PMID 39080260, 2024).
liver cancer (7 papers, 2019 to 2024). An epithelial or non-epithelial malignant neoplasm that arises from the liver. "HMGA1 activation also increases the cell viability and migration of liver cancer cells, indicating its driving role in liver carcinogenesis." (PMID 36685838, 2022). "Other studies also confirmed HMGA1 increases monotonously from normal liver to liver cirrhosis and then to liver cancer, both in mRNA and protein levels." (PMID 35864955, 2022).
anaplastic thyroid carcinoma (6 papers, 2014 to 2024). "Likewise, it has also been reported that trabectedin seems to downregulate the expression of HMGA1-targetted genes in anaplastic thyroid carcinoma." (PMID 38758230, 2024). "We demonstrated that HMGA proteins positively regulate ATM expression and the inhibition of HMGA1 expression through an antisense approach drastically decreases cellular levels of ATM in anaplastic thyroid cancer (ATC) cells, resulting in increased sensitivity to genotoxic agents." (PMID 25409711, 2014). "Conversely, anaplastic thyroid carcinoma (ATC), which is one of the most aggressive human tumours, expressed very high HMGA1P levels that, moreover, correlated with HMGA1 protein levels." (PMID 25268743, 2014). "Similar results were obtained with anaplastic thyroid carcinoma cells expressing or not HMGA1 proteins, treated with doxorubicin or the HDAC inhibitor LBH589." (PMID 25409711, 2014).